CCR7 (C-C motif chemokine receptor 7)
Diseases named in the same sentence as CCR7 in open-access papers (continued):
Sharing a sentence is not in itself a finding about the gene and the disease.
COVID-19 (continued). "Contrary to CARMIL2 and CCR7, consistent expression of NIBAN3, also known as B-cell novel protein 1 (BCNP1), in SAT under consideration of infection with and without vaccination lacks direct associations with obesity, T2D, or COVID-19." (PMID 38474155, 2024). "In line with that, our results show broad expression of CCR7 within the T cell population in the lungs of prolonged COVID-19, the time when absolute numbers of both CD4+ and CD8+ T cells are found significantly increased compared to all other disease groups analyzed." (PMID 36774347, 2023). "Higher expression of SAS-1 (SAS-1high) likely tracked IChigh, as this signature comprised IC-related genes (e.g., CCR7, IL7R) and higher baseline expression of SAS-1 associated with lower all-cause mortality hazards during acute COVID-19 as well as lower all-cause mortality hazards in the FHS." (PMID 37311745, 2023). "In summary, these comparisons show that the immune response – at the level of circulating immune cell frequencies and monocyte/DC surface marker expression – is highly similar between CAP and COVID-19, with the notable exception of CCR7 expression on classical monocytes." (PMID 38077404, 2023). "In the early stages of COVID-19, a low proportion of naïve CCR7 CD4+T cells may be an independent early predictor of patient death." (PMID 36420258, 2022). "The analysis of T-helper differentiation in peripheral blood revealed a relative loss of ‘naïve’ CD4 T cells (with CD45RA+CD27+CCR7+CD95− phenotype) but a significant increase in the amount of EM2 (CD45RA−CD27−CCR7+) and EMRA (CD45RA+CD27−CCR7−) cells in COVID-19 patients compared to controls." (PMID 35632823, 2022). "Moreover, it was found that the expression level of CD80, CD86, CCR7, and HLA-DR molecules was lowered on pDC and cDC1 examined in COVID-19 patients vs. healthy volunteers after in vitro stimulation with TLR-3, -7, or -8 ligands." (PMID 36146713, 2022). "Moreover, patients requiring mechanical ventilation vs. mild COVID-19 were noted to have lower percentages of CD45RA–CCR7– CD8+ T cells along with elevated levels of CD45RA+CCR7– TEMRA CD8+ T cells." (PMID 36146713, 2022). "In COVID-19 convalescent patients with sarcoidosis, we noted higher absolute numbers and percentages of CD45RA–CCR7– and CD45RA+CCR7– cells within Th subset." (PMID 41376646, 2025). "The CD4+ T cell population phenotypes in convalescent COVID-19 patients are predominantly central memory phenotype (CD45RO+, CCR7+), followed by an effector memory phenotype (CD45RO+, CCR7-)." (PMID 37091818, 2023). "The RS between activation marker concentrations and the severity of COVID-19 are calculated by training data set Z2KP, where the activation markers are IL-17a, IL-2, GATA3, IFN-γ, IL-4, IL-10, PD_1, CD40L, RORγt, CTLA_4, CCR7, TNF-α and IL-6, respectively." (PMID 36845115, 2023). "Compared with SARS-CoV-2– T cells, a fraction of SARS-CoV-2–specific CD4+ T cells expressed low/moderate levels of CCR7, which revealed the induction of distinct CD4+ T cell differentiation hierarchies after COVID-19 vaccination." (PMID 35230977, 2022). "The proportion of EM (CCR7+, CD45RA−, CD28+ and CD27+/−) CD8+ T cells known to have higher concentration of GZMK is significantly decreased in the first week of COVID-19." (PMID 34945761, 2021). "In addition, the SP group had a high suppressive score of all Tregs, CCR7+ Tregs, CD69+ Tregs, and CTLA4+ Tregs in severe COVID-19 patients." (PMID 40114921, 2025). "ILCp cells from COVID-19 patients showed upregulated expression of IL2RA (adj.p = 0.004), IL4R (adj.p = 2.3e-11) as well as other immune-related genes including TNFRSF25 (adj.p = 4.2e-03) and CCR7 (adj." (PMID 39026668, 2024). "Interestingly, an increased number of Naïve Tregs (CD45RA+CCR7+) and central memory Tregs (CD45RA−CCR7+) with strong PD-1 expression were reported in patients with COVID-19." (PMID 39519310, 2024).
COVID-19 (continued). "In the umbilical cord blood samples of children whose mothers tested positive for COVID-19 4–6 weeks before delivery (subgroup 1), the CD4+CCR7+ T cells increased with a concomitant decrease in the proportion of naive CD4+ T cells compared with the control group (p = 0.016)." (PMID 37445296, 2023). "Six hub genes (FCGR3A, CD69, IFNG, CCR7, CCL5, and CCL4) were involved in regulating immune cells in COVID-19 and HF, which may contribute to the pathogenesis of HF." (PMID 36420258, 2022). "Moreover, dendritic cells, obtained from patients with COVID-19, expressed significantly less CD80, CD86, CCR7, and HLA-DR in response to in vitro stimulation compared to those from HDs." (PMID 36012146, 2022). "In response to in vitro stimulation with ligands for TLR3, TLR4, TLR7, or TLR8, the key populations of DCs from COVID-19 patients (i.e., pDC, cDC1, and cDC2) expressed less CD80, CD86, CCR7, and HLA-DR than the cells from corresponding populations of apparently healthy volunteers." (PMID 35632823, 2022). "In particular, a lower percentage of the homing receptor integrin-β7+ (β7) and CD86+ DCs, as well as a higher percentage of the C-C chemokine receptor type 7+ (CCR7) and of the marker of immune tolerance and suppression indoleamine 2,3-dyoxigenase (IDO) were observed in COVID-19 patients." (PMID 35757770, 2022). "For example, we found that the chemokine receptor CCR7 was downregulated with hyper-methylation at the promoter, and transcription factor RUNX3 was upregulated with hyper-methylation in the gene body in recovery COVID-19 patients." (PMID 36263014, 2022). "The characterization of the T cell subsets in a cohort of 39 COVID-19 with a median age of 64 years (range 35–94) has revealed that a decrease in both the percentage and the absolute number of naïve CD45RA+CCR7+ CD8+ T cells and in the absolute number of naïve CD45RA+CCR7+ CD4+ T cells." (PMID 34595175, 2021). "However, while these stromal cells were the main subset expressing CCR8 in COVID-19 lungs, the CCR7 signal was not restricted to the stromal compartment." (PMID 36774347, 2023). "Immunostaining of COVID-19 brains revealed extensive activation of both microglia and astrocytes, severe damage of the blood–brain barrier (BBB) and various degrees of perivascular infiltration by predominantly CD14+/CD16+/CD141+/CCR7+/CD11c+ monocytes and occasionally CD4+/CD8+ T lymphocytes." (PMID 36609561, 2023). "However, in clear contrast with CAP, classical monocytes of patients with COVID-19 did not express more CCR7 than controls." (PMID 38077404, 2023). "The peripheral immune response in patients with COVID-19 was highly comparable to patients with CAP, yet lacked the increased expression of CCR7 on classical monocytes." (PMID 38077404, 2023). "In some COVID-19 patients without Foxp3, the levels of CD45RA+CCR7+ Tregs in some COVID-19 patients decreased, while the levels of activated CD45RA-CCR7+ Tregs increased." (PMID 36034704, 2022). "Moreover, enhanced CCR7 expression on classical monocytes was restricted to CAP and not present in COVID-19." (PMID 38077404, 2023). "Moreover, some COVID-19 patients showed a reduction in the levels of CD45RA+CCR7+ Tregs and an increase in the levels of activated CD45RA-CCR7+ Tregs, in the absence of Foxp3." (PMID 34631206, 2021).
lymph node metastasis (46 papers, 2005 to 2025). "A previous study using an animal model of CRC demonstrated that CCR7 expression was associated with lymph node metastasis." (PMID 40864806, 2025). "CCR7 shows significant associations with lymphatic infiltration, lymph node metastasis, tumor depth, and tumor-node metastasis (TNM) stage, all of which correlate with poor survival outcomes." (PMID 40134607, 2025). "CCR7 expression was significantly associated with disease stage, grade, lymph node metastasis, and perineural and vascular invasion." (PMID 39001456, 2024). "This retrospective study was designed to underpin the importance of MMP-9 and CCR7 expression in predicting the risk of lymph node metastasis in the LSCC patients." (PMID 37600570, 2023). "VEGF-C and VEGF-D expression correlated with CCR7 levels and was associated with esophageal and lung cancer progression, respectively, with increased lymph node metastasis and reduced patient survival." (PMID 35203305, 2022). "Higher expression of CCR7 is associated with recurrence, lymph node metastasis, and poor patient survival in ESCC." (PMID 33390169, 2021). "They found that CCR7 expression was significantly associated with T stage and lymph node metastasis." (PMID 30781353, 2019). "The association between CCR7 markers and lymph node metastasis in the patients with thyroid and colorectal cancer was also found 7-9." (PMID 30233771, 2018). "We show that CCR7 expression is associated with lymph node metastasis (P = 0.022) and overall survival (OS; P = 0.025), and is an independent factor associated with poorer overall survival (P = 0.032)." (PMID 26176983, 2015). "The CCL21/CCR7 axis has been associated with lymph node metastasis of several cancers, including breast (for review see:)." (PMID 23667660, 2013). "High CCR7 expression in gastric cancer cells was significantly associated with poor overall survival (OS) (P = 0.010) and lymph node metastasis (P = 0.009), and was an independent factor for worse OS (P = 0.023) by multivariate analysis." (PMID 24040244, 2013). "The authors theorized that CCR7 is associated with lymph node metastasis, while CXCR4 expression aids in the reliability of CCR7 as a biomarker." (PMID 22295222, 2011). "Other cell adhesion molecular markers associated with lymph node metastasis, such as the chemokine receptors CCR7, CXCR3 and CCL21, could be related to distant metastasis development." (PMID 28705152, 2017). "It was demonstrated that CCR7 is associated with lymph node metastases of the malignancies." (PMID 27009073, 2016). "We hypothesized a clinicopathological correlation and functional causality between CCR7 expression and lymph node metastasis in patients with esophageal squamous cell carcinoma (ESCC)." (PMID 24766770, 2014). "CCR7 also positively associated with lymph node metastasis in patients with tonsillar SCC and OSCC." (PMID 24212639, 2011). "Other cell-adhesion-molecular markers associated to lymph-node metastasis, as chemokine receptors CCR7, CXCR3 and CCL21, could be related to brain metastasis development, thus, studies about analysis of their association with brain metastasis development are justified." (PMID 19386089, 2009). "CCR7 expression was also found to correlate with a worse overall prognosis in patients, showing increased levels in those with lymph node metastasis, as well as higher tumor stage and grade." (PMID 39409924, 2024). "The analysis of MMP-9 and CCR7 expression performed in this study has extended our knowledge on the potential of these markers in predicting the lymph node metastasis in LSCC." (PMID 37600570, 2023). "Using this value as our cut-off point implies that the sensitivity of CCR7 in predicting the lymph node metastasis was 100%, and the specificity was 80%." (PMID 37600570, 2023). "Further, various cancer types overexpressing CCR7 have been reported to have a poor prognosis owing to accelerated lymph node metastasis." (PMID 36307918, 2023).
lymph node metastasis (continued). "The expression of both MMP-9 and CCR7 was significantly correlated with the lymph node metastasis in LSCC (P<0.001)." (PMID 37600570, 2023). "A clinical trial of a small molecule antagonist of CCR7 inhibiting lymph node metastasis is currently underway." (PMID 36307918, 2023). "When levels of CCR7 mRNA were measured in primary human invasive breast cancers, patients with lymph node metastases showed elevated ET-1 and CCR7 expression." (PMID 35203305, 2022). "In OSCC patients, the overexpression of CCR7 positively correlated with lymph node metastasis and M2 macrophage infiltration." (PMID 35904690, 2022). "Further, a significant association between CCR7, VEGF-C, and VEGFR-3 expression and lymph node metastasis were observed." (PMID 35203305, 2022). "High CCR7 expression significantly correlated with cervical lymph node metastasis and histological grade of tongue squamous cell carcinoma." (PMID 35203305, 2022). "Clinical gastric cancer specimens had a similar propensity for CCR7 expression (42/64, 66%), which correlated with lymph node metastasis." (PMID 35203305, 2022). "Elevated expression of CCR7 or its ligand CCL19 in colorectal or gastric cancer correlated with lymph node metastases, and an improvement in overall survival." (PMID 35203305, 2022). "A second study reported a similar positive correlation between CCR7 levels and lymph node metastasis in pancreatic cancer tissue from patients." (PMID 35203305, 2022). "Looking not only at primary tumors but also recurrences, lymph node and distant metastases of ACCs, the H-score for CCR7 was significantly higher in lymph node metastases compared to primary tumors, recurrences, and distant metastases (all p < 0.01)." (PMID 34830848, 2021). "In contrast to several studies focusing on immunohistochemical expression of CCR7 in malignant tumors, we were not able to demonstrate significant differences in the rate of lymph node metastasis between patients with low and high CCR7 protein." (PMID 34830848, 2021). "Chemokine CCL21 and its unique receptor CCR7 had been described as vital factors determining cancer lymph node metastasis, and they were observed elevated in colorectal liver metastases." (PMID 33878734, 2021). "For instance, previous studies have shown that CCR7 was correlated with lymph node metastasis in patients with CC and was an excellent therapeutic target in cancer." (PMID 34108992, 2021). "The combined evaluation of CCR7 and CT appeared to be a more reliable marker for lymph node metastasis in BCa than the diagnosis by CT or CCR7 alone." (PMID 33869048, 2021). "While the overexpression of CXCR4/CXCL12 is correlated with the homing of cancer cells to the liver, lung, bone marrow and lymph nodes, the overexpression of the CCR7/CCL21 axis has mainly been related to lymph node metastasis." (PMID 32340161, 2020). "In other words, there was a significant correlation among the CCR7 expression, level of lymph node metastasis and disease stage." (PMID 30233771, 2018). "The result suggested a positive correlation of CCR7 expression with patient baseline lymph node metastasis and TKI drugs response." (PMID 28114889, 2017). "Consistent with former research, CCL21/CCR7 was highly expressed in cancer tissues, especially in patients with lymph node metastasis." (PMID 27505247, 2016). "Higher expression of CCR7 was associated with American Joint Committee on Cancer (AJCC) staging and lymph node metastasis." (PMID 27009073, 2016). "Meanwhile, in the 89 patients with lymph node metastasis, 53 patients co-expressed CCR7 and MUC1 (59.6 %), seven patients only expressed CCR7 (13.2 %), 18 patients only expressed MUC1 (20.2 %), and 11 patients did not express CCR8 or MUC1 (12.4 %)." (PMID 26667143, 2015). "In 89 patients with lymph node metastasis, there were 60 (67.4 %) patients with positive CCR7 expression, and 67 (75.3 %) patients with positive MUC1 expression." (PMID 26667143, 2015).
lymph node metastasis (continued). "The CCR7(+) patients exhibited a significantly higher rate of lymph node metastasis (p = 0.037) and a poor five-year overall survival (OS, 53.2% versus 25.0%, p = 0.013)." (PMID 24766770, 2014). "First, we demonstrated that positive CCR7 expression was significantly correlated with lymph node metastasis and the five-year survival rate using the largest population of patients with ESCC." (PMID 24766770, 2014). "The immunohistochemistry results also showed that the phosphorylation of STAT3 was correlated with CCR7 expression in SCCHN, and CCR7 and STAT3 phosphorylation were all associated with lymph node metastasis." (PMID 25405202, 2014). "The CCR7(+) group had significant correlations with lymph node metastasis (p = 0.040) and the histological grade (p = 0.020) as well as lymphatic and vessel invasions (p = 0.044 and p = 0.045, respectively)." (PMID 24766770, 2014). "The present data are consistent with previous studies that describe a positive correlation between CCR7 expression and lymph node metastasis in cases of breast, colorectal, esophageal and prostate cancer and oral and oropharyngeal squamous cell carcinoma." (PMID 23761820, 2013). "Positive correlation has likewise been reported between CCR7 expression and lymph node metastasis in cases of NSCLC, breast, gastric, colorectal, esophageal, and thyroid cancer." (PMID 20181250, 2010). "Meanwhile, CCR7 was positively expressed in the cytoplasm, and the activity was significantly correlated with lymph node metastasis (P < 0.001)." (PMID 20181250, 2010). "In particular, they advocated a role for chemokine receptor 7 (CCR7) in lymph node metastasis, CXCR4 in pulmonary metastasis, and CCR10 in skin metastasis." (PMID 15978137, 2005). "The expression of CCR7 on non-immune cells has been linked to lymph node metastasis in various malignancies, including colon cancer, breast cancer, head and neck squamous cell carcinoma, and melanoma." (PMID 39409924, 2024). "Notably, in the context of PCa, TNF-α has been implicated in promoting cell migration via the upregulation of CCR7, particularly in cases of lymph node metastasis." (PMID 38484140, 2024). "Furthermore, CCR7 expression exhibited the highest prediction accuracy (AUC 95.7%) and sensitivity (100%) in predicting the lymph node metastasis in LSCC compared to that of MMP-9 (AUC 92.9%, sensitivity 90%)." (PMID 37600570, 2023). "Additionally, we found that there was a correlation between the staining level of CCR7 and lymph node metastasis in tongue cancer samples." (PMID 36307918, 2023). "Analysis of microdissected pancreatic cancer samples found that expression of CCR7 was associated with lymph node metastasis and tumors that lacked CCR7 had low rates of lymphoid tissue invasion." (PMID 35203305, 2022). "Similarly, high expression of CCR7 are shown to correlate with lymph node metastasis in pancreatic and many other cancers." (PMID 35433680, 2022). "In clinical lung adenocarcinoma tissue samples, both CCR7 and CXCR3 were expressed, with CXCR3 having a higher frequency, 90% vs. 65%; however, only CCR7 was associated with lymph node metastasis and not CXCR3 in these human tissues." (PMID 35203305, 2022). "In head and neck cancers, VEGF-C and CCR7 co-expression correlated with lymph node metastasis." (PMID 35203305, 2022). "However, VEGF-C co-expression with CCR7 was a strong predictor of lymph node metastasis, and a meta-analysis of 15 studies found that CCR7 is a marker of a poor prognosis." (PMID 35203305, 2022). "Moreover, a possible correlation of CCR7 high expression and patients’ baseline and post-administration lymph node metastasis was found." (PMID 28114889, 2017). "Consistent with our results, previous reports support the conclusion that CCR7 could promote lymph node metastasis." (PMID 27009073, 2016).